CXCL12 (C-X-C motif chemokine ligand 12)
Diseases named in the same sentence as CXCL12 in open-access papers (continued):
Sharing a sentence is not in itself a finding about the gene and the disease.
cancer (continued). "For such TEM to occur, the cancer cell must be able to make a local trip along a CXCL12 gradient to approach the vascular vessels." (PMID 26993780, 2016). "Significant upregulation of mir31 and downregulation of its target gene, CXCL12, in cancer, LK and LP tissues suggest their importance in progression of precancer to cancer." (PMID 27597234, 2016). "On the contrary to our results, some authors concluded that the CXCL12 and its receptor levels depended on the amount of cancer cells; however these findings were performed on EC tissue using immunohistochemistry technique." (PMID 27041792, 2016). "The antinucleolin aptamer AS1411 and the antistroma cell-derived factor-1 (SDF-1 also called CXCL12) NOX-A12 are among the most advanced aptamers for cancer treatment." (PMID 27413756, 2016). "In lung cancer, CAFs promote the proliferation and invasiveness of cancer cells by high expression of Forkhead box F1 and CXCL12.CAFs from squamous cell carcinoma of the head, neck and esophagus secrete hepatocyte growth factor to promote cancer invasion." (PMID 26954362, 2016). "Among major immune checkpoints, e.g. PD-1 and CTLA4, the pharmacologic blockage of CXCR4 and its endogenous ligand CXCL12 has appeared as a prime target for blocking strategies in the treatment of cancer patients." (PMID 27462860, 2016). "So, expression deregulation of miR-31 and its target gene (CXCL12) in pre-cancer and cancer tissues suggest for a common mechanism leading to these diseases." (PMID 27597234, 2016). "Cancer cells expressing CXCR4 form distant metastases in secondary organs that produce high levels of CXCL12, in human specimens and murine models." (PMID 26744352, 2016). "The increased concentration of CXCL12 in the cancer microenvironment creates a network of dense stroma restricting immune cells migration and recognition of cancer antigens." (PMID 26981244, 2016). "Recent studies have drawn much attention to CXCR4-high cancer cell metastasis to CXCL12-rich tissues suggesting that such cancer cells have hijacked the CXCL12- guided mechanism of cell homing to establish metastasis." (PMID 26993780, 2016). "Its ligand, CXCL12, is also secreted by CRC cells, but the significance of CXCL12 expression by cancer cells remains controversial so far." (PMID 27136535, 2016). "Although CXCL12 and CXCR7 were revealed to be associated with outcomes in some kinds of cancer, data about their prognostic values in PC, one of most lethal malignancies, remain to be exploratory, even controversial." (PMID 27542220, 2016). "Several studies have reported the relationship between CXCL12 and invasion of malignant tumors other than ESCC." (PMID 27439769, 2016). "So, expression deregulation of miR-31 and its target gene (CXCL12) seems to have significance in the progression of pre-cancer to cancer, but it needs to be validated in a larger set of samples with follow-up data." (PMID 27597234, 2016). "AMD3100 is not toxic to host cells at concentrations up to 500 mM and the CXCL12/CXCR4 blockade efficiently decreases cancer cell proliferation." (PMID 27439769, 2016). "Except OSMF, expression of only one target gene (i.e. CXCL12) of miR-31 was significantly deregulated in both cancer and two other pre-cancer tissues." (PMID 27597234, 2016). "Chemokine (C-X-C motif) receptor 7 (CXCR7) and its ligand, chemokine (C-X-C motif) ligand 12 (CXCL12), were established to be involved in biological behaviors and associated with prognosis in many cancers." (PMID 27542220, 2016). "Several in vitro and in vivo models have revealed a key role of chemokine receptor 4 (CXCR4) and its ligand CXCL12 in the crosstalking between cancer cells and their microenvironment." (PMID 26920352, 2016). "Expression of the target genes (DMD and CXCL12) was also downregulated in precancers and cancer tissues probably due to upregulation of mir31 in these tissues." (PMID 27597234, 2016).
cancer (continued). "Several studies by other groups have demonstrated that the expression of CXCR4 or CXCL12 in cancer cells worsens the prognosis in patients with ESCC." (PMID 27439769, 2016). "In a genetically engineered mouse model of PDAC blocking the receptor of CXCL12, induced rapid T cell accumulation and synergized with anti-PD-L1 in cancer cell killing." (PMID 27655706, 2016). "For example, CXCR7, which is a novel receptor of CXCL12, was reported to be involved in the progression of several carcinomas." (PMID 27439769, 2016). "Interferon-γ reduced CXCR4 expression on cancer cells and inhibited the CXCL12-induced cell migration." (PMID 25609202, 2015). "CXCR7 regulates CXCL12/CXCR4-mediated cell motility by scavenging CXCL12, both during normal processes (e.g., development) and in the diseased state (e.g., cancer)." (PMID 25884570, 2015). "In fact, blockade of CXCR4 only partially inhibited migration of cancer cells to CXCL12 gradients in vivo because the relationship between CXCR7 (the secondary receptor of CXCL12) and CXCR3 via their shared ligand CXCL11 has made this interaction more complex." (PMID 26062132, 2015). "CXCR7 is another receptor for CXCL12 with rather high binding affinity and is reported to be involved in cancer cell proliferation in a CXCR4-independent and/or-dependent manner." (PMID 26083776, 2015). "CXCL12 is an important chemokine that participates in the regulation of tissue homeostasis, immune surveillance, cancer development, and the regulation of inflammatory responses." (PMID 26648938, 2015). "In cancer cells, decreased miR-126/126* expression results in an increased production and secretion of CXCL12 that in turn attracts MSCs to the tumor microenvironment and increases the secretion of CCL2." (PMID 25743773, 2015). "Another promising targets is CXCR4, which is expressed on many types of cancer cells and works as a receptor for stromal cell-derived factor 1 (SDF1; also termed CXCL12)." (PMID 26496035, 2015). "The function of filopodia in decoding the Cxcl12a gradient in the context of PGC migration must bear on cancer cell invasion, since Cxcl12 is known to play a key role in metastasis of several cancer types." (PMID 25875301, 2015). "In the last years there is an increasing interest on the interaction of the cancer cells with their microenvironment, mediated by the chemokine ligand CXCL12, and its chemokine receptor 4 (CXCR4)." (PMID 25613038, 2015). "We found that nerve tissues in the PCa specimens with PNI highly express CXCL12, and the cancer cells that expressed the CXCR4 receptor are arranged around nerves." (PMID 25605248, 2015). "The CXCR4/CXCR7/CXCL12 chemokine axis has been involved in the progression and organ-specific dissemination of various cancers." (PMID 25955316, 2015). "Despite the evidence importance of this finding for T1D treatment, it should be noted that local immunosuppression achieved through CXCL12 has also been observed in cancer models where this mechanism protects cancer cells from immune attack." (PMID 26300887, 2015). "On the other hand, the convergence of the CXCL12/CXCR4 axis in several studies of multiple tumors suggested the use of CXCR4 inhibitors in the treatment of cancer." (PMID 26062132, 2015). "Some of these cancer-related genes were associated with processes occurring in the extracellular matrix and related to DCN: CXCR4/CXCL12 axis, SELP, vWF, COL3A1, SCARA, SPARCL1." (PMID 26437222, 2015). "This phenomenon is more obvious in the groups with the addition of exogenous CXCL12, where we observed a retrograde migration of the cancer cells along the contacting neurites after the neurite-cancer cell contact." (PMID 25605248, 2015). "The risk score was accompanied with the downregulation of several cancer-related networks, namely, CXCL12/CXCR4 pathway and JAK/STAT." (PMID 26078947, 2015). "Their interaction leads cancer cells to move toward metastatic sites that consist of CXCL12-enriched microenvironments." (PMID 29061949, 2015).
cancer (continued). "Although the signals generated by the metastatic niche that regulates cancer stem cells are not fully understood, accumulating evidence suggests a key role of the CXCL12/CXCR4 axis." (PMID 26576337, 2015). "Taken together, these results demonstrate that CXCL12 isoforms form gradients that differ in shape, magnitude and scope even within the disorganized pattern of cancer cells present in some tumors." (PMID 25909600, 2015). "Growing evidence indicates a role for CXCR7 in cancer cell proliferation and migration, however little is known as to the contribution of this binding receptor to CXCL12– mediated effects." (PMID 24497931, 2014). "For example, we and others have shown inhibition of CXCL12-induced migration of cancer cells by GABABligands." (PMID 24808825, 2014). "CXCR4-positive cancers metastasize to the lymph nodes, liver, and bones in a CXCL12-dependent manner." (PMID 24647809, 2014). "Chemokine CXCL12 promotes growth and metastasis of more than 20 different human cancers, as well as pathogenesis of other common diseases." (PMID 24896823, 2014). "The CXCL12/CXCR4 axis has been shown to promote cell survival by inhibiting apoptosis in cancer cells; thus, CTCE-9908-mediated inhibition of the CXCL12/CXCR4 pathway leads to loss of protection from apoptosis and increased cell death." (PMID 24472670, 2014). "For instance, CXCL9, CXCL12, PDGF-BB, and VEGF, all of which are well-known factors associated with cancer cell invasion, were also detected by the cytokine antibody array in this study." (PMID 25271422, 2014). "Its function in metastasis begins with cancer cell mobility—the binding of CXCL12 to CXCR4 activates various intracellular signal transduction pathways and effector molecules that regulate chemotaxis, migration, and adhesion." (PMID 25165728, 2014). "While CXCL12/CXCR4 activation within both cancer cells and local stroma clearly contributes to GBM cell proliferation, spreading, and survival to therapy, more recent studies demonstrated that CXCR7 is an alternative, or additional, regulator of GBM growth." (PMID 24904289, 2014). "CXCL12 concentration gradient directs cancer cell motility in several tumors, including aggressive solid neoplasms (breast, colon, brain ovarian, prostate, renal cell and oral squamous cell carcinomas, and melanoma)." (PMID 25484899, 2014). "CXCL12 regulates the homeostasis, angiogenesis, proliferation, survival and migration of cancer cells (16, 19 and 20)." (PMID 25237365, 2014). "The CXCR4/CXCL12-axis has been demonstrated to exhibit a critical role in the trafficking and homing of normal stem cells and metastasis of cancer stem cells to organs that express high levels of CXCL12, including the lymph nodes, lungs, liver and bone." (PMID 25202367, 2014). "High expression of the ligand for CXCR4, CXCL12/SDF-1, is detected in organs that are usually the primary destinations of metastasis for these cancers." (PMID 24941119, 2014). "The effect of COUP-TFI is mediated by the induction of MAPK signaling and leads to enhanced growth and migration capacity in cancer cells in response to CXCL12." (PMID 24906407, 2014). "The CXCR4, cell surface receptor for the chemokine CXCL12 (SDF-1), plays a central role in cancer cell proliferation, invasion, and dissemination in the majority of malignant diseases." (PMID 24921652, 2014). "Several groups found that CXCR4 and its ligand CXCL12 can promote the proliferation, survival, and invasion of cancer cells." (PMID 24810923, 2014). "It is well established that CXCR4+ cancers metastasize to the distant organs in a CXCL12/SDF-1-dependent manner." (PMID 24674692, 2014). "Although the pivotal role of the CXCL12/CXCR4 axis in cell motility and consequently in cancer metastasis in several tissues is well established, the contribution of CXCL12 via its receptor CXCR7 is less understood." (PMID 24906407, 2014).
cancer (continued). "Work from our laboratory was among the first to show a beneficial preclinical effect of autocrine CXCL12 on carcinoma malignancy." (PMID 24594697, 2014). "The CXCR4/CXCL12 axis plays a role in cancer metastases, stem cell mobilization and chemosensitization." (PMID 24058588, 2013). "Amongst the chemokine signalling axes involved in cancer, chemokine CXCL12 acting on chemokine receptor CXCR4 is particularly significant since it orchestrates migration of cancer cells in a tissue-specific metastatic process." (PMID 24205302, 2013). "CXCL12 was also commonly affected; it plays a role in cancer spread/metastases via interaction with its receptor CXCR4." (PMID 23372777, 2013). "Amongst the chemokine signalling axes involved in cancer, chemokine CXCL12, acting on chemokine receptor CXCR4 is particularly significant." (PMID 24205302, 2013). "Its ligand, CXCL12 is abundant in liver, bone and brain, which are the common sites of metastasis for cancers of these organs and tissues." (PMID 24205302, 2013). "The chemokine CXCL12/SDF-1 and its receptor, CXCR4, have been implicated in invasion, survival, and proliferation of carcinoma cells." (PMID 24363762, 2013). "Its ligand, CXCL12, is found in some primary tumour sites and sites of cancer metastasis and is also constitutively expressed by normal organs such as the bone marrow." (PMID 22272201, 2012). "Several lines of evidence support the clinical relevance of this chemokine receptor by demonstrating that CXCR4 promotes angiogenesis and site specific cancer metastasis to the favorable organs, where its ligand CXCL12 is abundantly expressed." (PMID 23071744, 2012). "Chemokine receptor CXCR4, together with its ligand CXCL12, plays critical roles in cancer progression, including growth, metastasis and angiogenesis." (PMID 23249693, 2012). "Recent studies have shown the involvement of the CXCL12/CXCR4 axis in the progression of several types of cancer." (PMID 23181100, 2012). "Third, we determined that CXCL12-driven increases in cancer cell proliferation can occur through either receptor and hence either signaling pathway." (PMID 22472349, 2012). "High expression of the CXCR4 receptor of chemokine CXCL12 in cancer cell lines has been related to invasiveness, malignancy, and homing." (PMID 22655200, 2012). "Several of the novel CXCL12-responsive phosphoproteins provide an attractive list of potential targets for the development of cancer metastasis and HIV-1 therapeutics." (PMID 23202899, 2012). "C-X-C-motif chemokine receptor 4 (CXCR4) and its ligand C-X-C-motif chemokine ligand 12 (CXCL12) have been shown to regulate an organ-specific metastasis by the formation of chemotactic gradients in several cancer." (PMID 22448123, 2012). "CXCR4, the specific receptor of CXCL12, is highly-expressed in cancer cells compared with homological normal tissue." (PMID 23443093, 2012). "There is a significant volume of literature demonstrating that CXCR4 and CXCL12 play critical roles in cancer metastasis in numerous types of cancers and it is important to develop anti-CXCR4 compounds to intervene in this progression." (PMID 22485156, 2012). "The CXCL12/CXCR4 pathway was originally discovered in the immune system to play an important role in cancer cell metastasis." (PMID 22074556, 2011). "CXCL12 is a pleiotropic chemokine involved in multiple different processes such as immune regulation, inflammatory responses, and cancer development." (PMID 21931802, 2011). "Several genes including AKT, TRAIL and CXCL12 are recognised as candidate genes for cancer stem cell progression and latent metastasis." (PMID 21342498, 2011). "Exposure of CXCR4+CXCR7+ cancer cells to CXCL12 greatly potentiated their TEM towards the chemokines CCL19 and CXCL13." (PMID 21672222, 2011).
cancer (continued). "Increasing evidence indicates that the interaction between the CXC chemokine receptor-4 (CXCR4) and its ligand CXCL12 is critical in the process of metastasis that accounts for more than 90% of cancer-related deaths." (PMID 21880153, 2011). "Metastasis is characterized by the ability of cancer cells to invade adjacent tissue, and is regulated by multiple signaling pathways, including the CXCL12/CXCR4 axis." (PMID 22074556, 2011). "It has been well documented that the CXCL12/CXCR4 signaling cascade plays a crucial role in cancer proliferation, migration and metastasis." (PMID 21880153, 2011). "CXCL12 is known to promote proliferation and survival of cancer cells in an autocrine and paracrine manner." (PMID 21695171, 2011). "Recently, the autocrine/paracrine CXCL12 stimulation of cancer cells was reported to restrain their migration behavior." (PMID 21695171, 2011). "There was a tendency for luminal cancers to show CXCL12 expression (102/138, 74%) compared to basal-like cancers (16/27, 59%), which verged on statistical significance (P = 0.050)." (PMID 21521526, 2011). "The CXCR4/CXCL12 axis can coordinate metastasis of a variety of cancers, such as bladder, breast, head and neck, ovarian, renal cell, and prostate." (PMID 22074556, 2011). "In the present work, CXCL12 expression was detected in benign tumors as well as in borderline and malignant tumors." (PMID 21410972, 2011). "In model systems, CXCR4 regulates cancer metastasis to lymph node, bone, liver, and lung, the four most common metastatic destinations, which also express high levels of CXCL12, the only known chemokine ligand for CXCR4." (PMID 21672222, 2011). "CXCL12 was originally described as a vital chemoattractant for B cells and monocytes but since has been shown to be involved in cancer progression." (PMID 20877573, 2010). "The current study defines a novel mechanism whereby CXCL12 redirects macrophages to promote a microenvironment that is suitable for cancer survival via a GM-CSF/HB-EGF paracrine loop." (PMID 20946648, 2010). "Within the tangle of relations between macrophages and cancer cells, we tried to tease out the role that CXCL12 plays in both cancer cells and macrophages at the boundaries between cancer and inflammation." (PMID 20946648, 2010). "Recently, the homeostatic chemokine CXCL12 has been shown to be an essential mediator of cancer metastasis, with our laboratory demonstrating that silencing of endogenous CXCL12 expression establishes a pro-metastatic phenotype." (PMID 20877573, 2010). "When these cancer cells were stimulated with 200 ng/mL CXCL12 and/or 25 ng/mL HB-EGF, they produced and released GM-CSF." (PMID 20946648, 2010). "In other types of cancer the physiological role of CXCR4/CXCL12, carried out during the embryonic development, is turned in the ability to influence cell migration and spreading in cancer." (PMID 20049170, 2010). "CXCL12 was shown to prompt mononuclear phagocytes and cancer cells to release HB-EGF and GM-CSF, respectively." (PMID 20946648, 2010). "Accumulating evidence indicates that CXCL12 and its receptors are involved in cancer development through the inhibition of apoptosis, and promotion of angiogenesis, cellular proliferation, invasion and metastasis." (PMID 20380740, 2010). "As a first step, we examined activity levels of the extrinsic apoptotic initiator, caspase-8, and intrinsic apoptotic initiator caspase-9 levels in carcinoma cells secreting varying amounts of CXCL12 (Hi, Med, Low)." (PMID 20877573, 2010). "Concurrently, CXCL12 protein levels are highest in common sites of metastasis including the liver, bone marrow, and lungs, suggesting that metastasis is the result of carcinomas indirectly hijacking chemokine-directed lymphocyte trafficking patterns." (PMID 20877573, 2010).